NTN1 (netrin 1)
Diseases named in the same sentence as NTN1 in open-access papers (continued):
Sharing a sentence is not in itself a finding about the gene and the disease.
cancer (continued). "Prior reports suggested that NTN1 is upregulated in several cancers, including PDAC, and directly promotes cancer cell growth and epithelial-mesenchymal transition (EMT)." (PMID 40777309, 2025). "Numerous studies have reported that netrin-1 exhibits increased expression in tumor cells and the tumor microenvironment, with its levels rising during cancer progression." (PMID 40723793, 2025). "Using pancreatic organoids, we demonstrate that NTN1 directly regulates PDAC growth through cancer cell NEO1 in an autocrine manner." (PMID 40777309, 2025). "Given DCC’s tumor-suppressive function, blocking Netrin-1/DCC interactions has emerged as a potential therapeutic approach to disrupting prosurvival signaling in cancer cells." (PMID 40243726, 2025). "In conclusion, our work underscores the importance of an axon guidance molecule in cancer cell-nerve interaction and demonstrates that the NTN1/NEO1 axis drives pancreatic tumorigenesis directly and indirectly through nerves." (PMID 40777309, 2025). "Netrin-1 appears to be a carcinogenic regulator in cancer, inhibiting tumor cell apoptosis and inducing tumor cell growth, migration, invasion, and metastasis." (PMID 40723793, 2025). "At the same time, NP137 can significantly inhibit tumor growth and metastasis in some cancer patients, so netrin-1 can be used as a potential therapeutic target for the disease." (PMID 40723793, 2025). "Consistent with our mT4 findings, NTN1 overexpression in Panc02 cells shortened mouse survival and increased the histological tumor burden and Ki-67+ proliferating cancer cells in a splenic injection model." (PMID 40777309, 2025). "Sufficient systematic studies have not been performed on the expression characteristics of the role of NTN1 and its receptors in the context of pan-cancer." (PMID 41407823, 2025). "We predicted the tie1 and tie2 fusion transcript of NTN1 and its receptor from the TumorFusions Database28 in TCGA cancers." (PMID 41407823, 2025). "As netrin-1 is considered to be a potential therapeutic target for cancer and inflammatory diseases, both macrophage-engineered exosomes and hydrogels can target macrophage-derived netrin-1 for treatment." (PMID 40723793, 2025). "The hot spot mutation P459T of NTN1 occurred in three patients with two cancers (STAD and READ), and the hot spot mutation R267C/G/H of MCAM occurred in four cancers (STAD, BLCA, UCEC, and LUSC)." (PMID 41407823, 2025). "Given the role of NTN1/NEO1 signaling in promoting the self-renewal of pluripotent stem cells, we evaluated the possible effects of the NTN1/NEO1 axis on cancer stemness." (PMID 40777309, 2025). "Our results showed the important cancer biological functions of NTN1 and its receptors and their transformational value as candidate tumor biomarkers." (PMID 41407823, 2025). "Our data suggest that NTN1 promotes the progression of primary PDAC through its direct influence on cancer cell FAK activation, EMT, and stemness, as well as through its indirect effects on nerves." (PMID 40777309, 2025). "In recent years, studies indicate that netrin-1 participates in angiogenesis, organ formation, inflammation regulation, and cancer progression by binding to its receptors." (PMID 40723793, 2025). "Although previous studies suggested that NTN1 promotes cancer cell growth and EMT through the UNC5B receptor, we found that NEO1, rather than UNC5B, was largely upregulated during mouse pancreatic tumorigenesis." (PMID 40777309, 2025). "The mutation distribution of NTN1 and its receptor members in CCLE (Cancer Cell Line Encyclopedia) was consistent with the TCGA data." (PMID 41407823, 2025). "In this review, we will summarize the recent research advances on the role of macrophage-derived netrin-1 and its receptors in a variety of inflammatory diseases and cancers." (PMID 40723793, 2025). "NTN1 and its receptors were correlated to the 28 types of TILs in many cancers, among which BLCA, KIRC, READ, and COAD were the most prominent." (PMID 41407823, 2025).
cancer (continued). "In that YAPon context, netrin suppresses the expression of oncogenic integrin β4 indicating netrin/integrin antagonism, which stands in stark contrast to YAPoff cancers in which our results reveal that Netrin-1 and integrins cooperate to inhibit proliferation." (PMID 39172021, 2024). "In contrast, mining transcriptome data from eight YAPon lines with YAP or YAP/TAZ knockdown revealed that YAP/TAZ do not upregulate these genes in that context, suggesting that YAP-induction of UNC5-family/NTN1 genes is YAPoff-cancer-specific." (PMID 39172021, 2024). "Forced YAP expression induced the expression of UNC5B and the related UNC5 family receptors, UNC5C and D, as well as their ligand NTN1/Netrin-1 in YAPoff cancers." (PMID 39172021, 2024). "Lastly, functional roles for Netrin-3,–4, and –5 are still relatively unexplored compared to Netrin-1, although their expression patterns suggest roles in advanced forms of some cancers." (PMID 39023520, 2024). "According to the globally largest and most comprehensive cancer mutation database (Catalogue of Somatic Mutations in Cancer, COSMIC), point mutations, copy number variation, high expression or methylation of NTN1 is found in almost 30 types of cancers." (PMID 38638604, 2024). "The current studies about Netrin-1 in the cancer field is moving rapid and more achievements can be expected in the near future." (PMID 38638604, 2024). "In animal models, downregulation of Netrin-1 or its receptors promotes cancer cell death and inhibits tumor growth." (PMID 38638604, 2024). "In cancer, the expression of Netrin-1 is largely altered in lesioned tissues, but its level in serum has not been extensively studied." (PMID 38638604, 2024). "Blocking the Integrin-αV/β5 dimer, either via gene deletion or with blocking antibodies, ameliorates YAP-induced cytostasis in YAPoff cancers, similar to the effects of inhibiting Netrin-1/UNC5 activity." (PMID 39172021, 2024). "Induction of UNC5-family and NTN1 in YAPoff cancers depended on YAP/TEAD-binding as YAPS94A, which cannot bind TEADs, failed to induce UNC5B, and a TEAD4(DBD)-VP64 fusion mimicked the effects of YAP." (PMID 39172021, 2024). "NP137, a netrin-1-blocking monoclonal antibody is currently in clinical trials for human cancer therapy (ClinicalTrials.gov identifier NCT02977195)." (PMID 38638604, 2024). "In preclinical models mimicking these diseases, interference between netrin-1 and its receptors was sufficient to trigger cancer cell death and induce tumour growth inhibition." (PMID 37532934, 2023). "Heterozygous amplifications and deletions are the main types of copy number variations in molecular VM-related DEGs in pan-cancer, among which the copy numbers of NTN1, SIPR1, LAMTOR5, and ZRANB2 are heterozygous deletions in most tumors." (PMID 37197406, 2023). "Used as a tumor biomarker, Netrin-1 is highly expressed in cancers, and especially in aggressive cancers." (PMID 37046702, 2023). "Netrin-1, which is expressed mainly during embryonic development, has been shown to be re-expressed by both cancer cells and the tumour microenvironment in a large proportion of human neoplasms." (PMID 37532934, 2023). "Still, our comprehensive bioinformatics analysis of cancer–nerve crosstalk-associated genes in SKCM constructed a valuable prognostic model based on eight genes (GRIN3A, CCR2, CHRNA4, CSF1, NTN1, ADRB1, CHRNB4, and CHRNG) and common clinical characteristics." (PMID 37404751, 2023). "These preclinical data support the view that netrin-1 blockade has a dual action on tumour cells: triggering of cancer cell death and inhibition of EMT features, rendering overall NP137-treated tumours more epithelial." (PMID 37532934, 2023). "Inhibition of intercellular signaling between cancer cells and CAFs using Netrin-1-mAb suppresses the expression of CAF-borne cytokines such as IL-6." (PMID 37065872, 2023). "Accumulating evidence supports NTN1 and its dependence receptors as potential targets for cancer therapy." (PMID 37446017, 2023).
cancer (continued). "Based on previous results suggesting that netrin-1 blockade is a viable therapeutic strategy in cancer, a netrin-1-blocking antibody was developed for clinical use13 and is undergoing Phase I/II evaluation." (PMID 37532934, 2023). "In intestinal cancer, DCC suppresses tumor growth by inducing cancer cell death when netrin-1 expression is low." (PMID 36499024, 2022). "The axon guidance factor netrin-1 has been reported to be involved in the tumorigenesis of many types of cancers." (PMID 35974411, 2022). "In particular, the Netrin-1 protein which is the ligand of several apoptosis-inducing dependence receptors is described as a key therapeutic target in many types of cancer and an anti-netrin-1 therapeutic antibody is currently being tested in the clinic." (PMID 35883457, 2022). "Netrin-1 has been reported to act as a novel promotor of cancer cell survival and invasiveness by inhibiting apoptosis through its receptors, such as DCC, Unc5 homologues (Unc5a, Unc5b, Unc5c and Unc5d) and Neo1." (PMID 35974411, 2022). "Netrin-1 signaling was found to participate in the invasion and migration of malignant cells in multiple types of cancer." (PMID 35974411, 2022). "In some human cancers, neoplastic cells can lose the ability to induce apoptosis by overexpressing netrin-1, or by decreasing the receptor expression." (PMID 36136711, 2022). "One of the ligands of UNC5A, netrin-1 is known to be overactivated in cancers, especially in inflammation-driven tumors." (PMID 36551254, 2022). "In parallel to the clinical activity, the Mehlen team is trying to define further the precise mode of action of the netrin-1 antibody considering its impact on cancer cell death and phenotypic plasticity." (PMID 35883457, 2022). "Nowadays, there is a growing collection of information regarding the different biological roles that NTN1 displays in a variety of cancer types." (PMID 33724150, 2021). "Both in vitro and in vivo approaches have shown that Netrin-1 promotes tumor progression, metastasis, and angiogenesis in cancer." (PMID 34361013, 2021). "The inhibition of netrin-1 in colon cancer inhibits the increase of CAFs, resulting in decreased cancer stemness and plasticity." (PMID 35008701, 2021). "Netrin-1 is a secreted protein that is well known for its involvement in axonal guidance during embryonic development and as an enhancer of cancer cell metastasis." (PMID 33883596, 2021). "According to these results, they proposed Netrin-1 upregulation as a survival mechanism of cancer cells in response to these drugs." (PMID 33126652, 2020). "It is worth noting that the mutations and potential mirRNA targeting of NTNG1 and NTNG2 in cancer exhibit rates that are much higher than those predicted for NTN1 and NTN4." (PMID 32251318, 2020). "Netrin-1 has been described as a key molecule in many different contexts, ranging from cancer progression, branching and membrane extension on oligodendrocytes, axon outgrowth in neurons to osteoclast differentiation in bone and angiogenesis." (PMID 30897795, 2019). "Deleted in colorectal cancer (DCC) is identified as the receptor that mediates Netrin-1-induced neuronal sprouting." (PMID 31822662, 2019). "Beyond its role in axon guidance, cell migration, and confinement, Ntn1 modulates angiogenesis and tissue morphogenesis, cell adhesion, synapse formation, and cell survival in cancer." (PMID 29444422, 2018). "Within recent years NTN1 has shown out to be essential for the tumorigenesis of different cancers including neuroblastoma, non-small cell lung cancer, pancreatic adenocarcinoma, metastatic breast cancer and colorectal cancer." (PMID 28069038, 2017).
cancer (continued). "Netrin-1 is involved in the survival mechanisms of various human cancer cell lines before it is silenced by siRNA." (PMID 29321724, 2017). "Extracellular guidance molecule netrin-1 promotes the invasiveness and survival of various cancer cell types." (PMID 28069038, 2017). "Here, we observed similar NTN1 mediated regulation of cancer stem-like cell motility and self-renewal." (PMID 28069038, 2017). "“Dependence receptors” are a class of receptors that auto-activate and trigger apoptosis in the absence of their ligands, and “dependence receptor” ligands such as Netrin-1 are known to be overactivated in cancers, especially in inflammation-driven tumors." (PMID 27031829, 2016). "Our work, therefore, illustrates a pathogenic positive feedback loop involving HCV, Netrin-1, and EGFR, among other factors, in association with cancer development." (PMID 27031829, 2016). "In a number of human cancers, NTN1 upregulation inhibits apoptosis induced by its so‐called dependence receptors DCC and UNC5H, thus promoting tumor progression." (PMID 27378792, 2016). "The fact that Netrin-1 fosters HCV entry through fostering EGFR activation is in agreement with previous reports on the involvement of Netrin-1 in cancers, in which dysregulated EGFR expression and signaling play a major role." (PMID 27031829, 2016). "Data obtained indicated that the 5′‐end CpGis of DAPK1 and NTN1 were methylated in the two cancer cell lines." (PMID 27378792, 2016). "In a substantial part of human cancers, netrin‐1 (NTN1) is upregulated and this upregulation is inhibiting apoptosis induced by its so‐called dependence receptors, DCC and UNC5H, and thus promotes tumor progression." (PMID 27378792, 2016). "Alternatively, in some types of cancers, an upregulation of NTN1 provides a similar tumor growth selective advantage by abolishing their dependency on netrin‐1 availability in the micro‐environment." (PMID 27378792, 2016). "The axon guidance factor netrin-1 promotes tumorigenesis in multiple types of cancers, particularly at their advanced stages." (PMID 27034160, 2016). "Previous studies have demonstrated Ntn1 promotes cell invasiveness, angiogenesis and cancer progression." (PMID 25909166, 2015). "UNC5A, UNC5B and UNC5C, which are the receptors of netrin 1, are all down-regulated in various cancers through promoter methylation." (PMID 26294325, 2015). "The differential expression of netrin-1 in our experimental cancer cells was confirmed byimmunofluorescence and western blot analysis." (PMID 26393880, 2015). "ACTG2, EZR, CNN1, DES, MS4A12 and NTN1 are all expressed at significantly higher levels in normal tissue compared to adenomatous polyp or carcinoma tissues." (PMID 25423035, 2014). "The fact that both netrin-1 and its receptors are upregulated upon conventional drug treatments suggests that the dependence for survival on netrin-1 is amplified in chemotherapy-treated cancer cells." (PMID 24293316, 2013). "We show that candidate drugs interfering with netrin-1/netrin-1 receptors interactions potentiate Doxorubicin, Cisplatin or 5-Fluorouracil-induced cancer cell death in vitro." (PMID 24293316, 2013). "Previous works have shown that a sizeable fraction of human cancer showed upregulation of netrin-1 as a selective mechanism to block tumour cell death." (PMID 24293316, 2013). "Netrin-1, a soluble protein initially discovered as an axon navigation cue, was recently proposed to play a crucial role in cancer progression by regulating apoptosis." (PMID 24293316, 2013). "Doxorubicin and 5FU both triggered a significant (i.e. >2-fold over control) increase of netrin-1 respectively in 53 and 47% of cancer cell lines." (PMID 24293316, 2013). "The secreted factor netrin-1 is upregulated in a fraction of human cancers as a mechanism to block apoptosis induced by netrin-1 dependence receptors DCC and UNC5H." (PMID 24293316, 2013).
cancer (continued). "Furthermore, Netrin-1 supports cancer cell stemness, counteracted by bone morphogenetic protein (BMP) signaling, suggesting a dynamic interplay between these pathways in shaping tumor behavior." (PMID 40243726, 2025). "Netrin-1 is the most studied and its misregulation in cancer leads to pro-survival signals." (PMID 39023520, 2024). "Netrin-1 is a secreted protein initially described as a neuronal navigation cue, which was more recently propose to promote tumor progression in multiple human cancers." (PMID 39172021, 2024). "Netrin-1 is often highly expressed in cancer tissues and involved in tumorigenesis as an oncogene." (PMID 38638604, 2024). "They hypothesized that NTN1 activated downstream signalling pathways in hypoxic HCC cells, causing EMT and the generation of numerous inflammatory mediators, which promote cancer invasion." (PMID 38546656, 2024). "Among them, Cspg5, Fbn1, Thbs1, Pdpn, Etv4, Unc5a, Ntn1, and Nat8l were associated with the OC prognosis; Cspg5, Fbn1, Pdpn, and Unc5a were correlated with patient age; Fbn1, Mycn, Nat8l, Unc5a, and Ntn1 were significantly correlated with individual cancer stage." (PMID 36829196, 2023). "Netrin-1 is upregulated in cancers as a protumoural mechanism." (PMID 37532934, 2023). "Netrin-1 regulates cancer cell proliferation through the multiple signal transduction pathways." (PMID 37038247, 2023). "Indeed, netrin-1 was previously considered to be an embryonic secreted molecule re-expressed in cancer settings to promote tumour cell survival." (PMID 37532934, 2023). "Existing reports indicate that Netrin-1 can activate ERK1/2 signaling in some types of cancer." (PMID 36361539, 2022). "Furthermore, Netrin-1 regulates cancer cell motility and tumorigenesis via multiple pathways, including YAP signaling 78, ERK/MAPK signaling 79, 80 and Notch signaling." (PMID 36147476, 2022). "Netrin-1 has also been reported to be overexpressed and to promote cancer in many other contexts." (PMID 33883596, 2021). "Netrin-1 has been proposed as a possible biomarker for different types of cancer." (PMID 34361013, 2021). "Netrin-1 is a multifunctional secreted glycoprotein upregulated in various cancers, such as gastric and lung, and may inhibit apoptosis induced by the dependence receptors DCC and UNC5H." (PMID 34503172, 2021). "Furthermore, Ntn1 has been described to support immature states of iPSCs and cancer stem cells, suggesting that it maintains stemness in various settings." (PMID 33504783, 2021). "Inhibition of netrin-1 abrogates CAF-mediated increase in cancer stemness." (PMID 34503172, 2021). "Our results reveal a previously unrecognized function of netrin-1 that may help to explain several of the developmental, physiological, and cancer-promoting functions of netrins at the signal transduction level." (PMID 33883596, 2021). "In cancer, Netrin-1 has a double role: it is a survival factor and a promoter of cell invasion." (PMID 32545553, 2020). "For example, binding of netrin-1 to deleted in colorectal cancer (DCC), possibly together with Unc5, repels migrating GABAergic neurons from the ventricular zone of the ganglionic eminence, whereas binding to α3β1 integrin promotes cortical interneuron migration." (PMID 33520982, 2020). "Although many aspects of NTN1 biology in cancer have been thoroughly investigated, the role of netrin isoforms is not well understood and could be helpful in designing therapy targeting pathological specific angiogenesis or cell survival." (PMID 30923634, 2019). "A link between inflammation and cancer was found in NTN1 expression in some colorectal cancers." (PMID 30923634, 2019). "On the other hand, upregulation of netrin-1 is observed in some types of cancers." (PMID 30532711, 2018). "If netrin-1 is the responsible factor for sunitinib resistance in mRCC, then we hypothesize that the downregulation of netrin-1 should result in decreased cancer cell migration and thus reduce disease progression in mRCC." (PMID 29854303, 2018).